FGL2 (fibrinogen like 2)
Diseases named in the same sentence as FGL2 in open-access papers (continued):
Sharing a sentence is not in itself a finding about the gene and the disease.
infection (15 papers, 2010 to 2026). The state of being infected such as from the introduction of a foreign agent such as serum, vaccine, antigenic substance or organism. "Novel EMT proteomic biomarkers (keratins 2, 6A and 20, collagen 12A1, desmoplakin) and inflammatory biomarkers (PSMB9, FGL2) were associated with early infection and barrier dysfunction." (PMID 36639424, 2023). "Surprisingly, significantly higher levels of FGL2 were observed after infection in all of PD-1-deficient organs, including the liver, thymus, spleen, lymph nodes, and serum than that in those from WT littermates." (PMID 21750671, 2011). "Western-blot was used to verify the higher FGL2 protein level in the livers of PD-1-deficient mice, as compared to WT littermates after 72 h of infection." (PMID 21750671, 2011). "Considering this, our results strongly indicate that the mortality of PD-1-deficient mice post-MHV-3 infection is due to the higher level of FGL2 secretion and increased fibrinogen deposition." (PMID 21750671, 2011). "Moreover, the level of FGL2 present in serum, as measured by ELISA, was found to increase rapidly after infection, and the level in PD-1-deficient mice was significantly higher than that in WT littermates." (PMID 21750671, 2011). "In addition, the transcription of fgl2 in the spleen of PD-1-deficient mice was also significantly increased in response to infection." (PMID 21750671, 2011). "To clarify whether the tissue necrosis we observed in PD-1-deficient mice following infection was also mediated by FGL2, the expression of FGL2 was analyzed." (PMID 21750671, 2011). "Moreover, treatment with antibody to FGL2 fully protected susceptible animals from the lethality of the virus, and adoptive transfer of wild-type Treg cells into resistant fgl2-deficient animals accelerated their mortality post-infection." (PMID 23908776, 2010). "s) infection model and samples from patients exhibiting mucosal immune responses (the early stage of COVID-19 infection), we investigated the function of Fgl2 in mucosal immunity." (PMID 41930335, 2026). "We found that the expression of Fgl2 in the liver of mice was reduced 72 h after MHV-3 infection and treatment with CC10 protein." (PMID 30619295, 2018). "Comparative analysis of E. multilocularis growth in fgl2-/- mice versus WT mice at the late stage of infection showed clearly that AE-WT mice exhibited a significantly higher parasite load as compared to AE-fgl2-/- mice." (PMID 25955764, 2015). "Key parameters for infection outcome in E. multilocularis-infected fgl2-/- (AE-fgl2-/-) and wild type (AE-WT) mice at 1 and 4 month(s) post-infection were (i) parasite load (i." (PMID 25955764, 2015). "At the late stage of infection (4 months- p.i.), fgl2-/- mice exhibited a significantly lower parasite load compared to WT mice, and 14-3-3 expression levels in AE-fgl2-/- mice were significantly lower those in AE-WT mice." (PMID 25955764, 2015). "We propose that the increased maturation of DC in fgl2−/− in the early stage of the infection contributed to the augmented anti-viral T cell responses compared to fgl2+/+ mice." (PMID 24146739, 2013). "Expression levels of the DC maturation markers CD80 and MHC class II were assessed on DC which were isolated from spleens and lymph nodes of LCMV-infected fgl2+/+ or fgl2−/−mice on day 1 post LCMV WE infection." (PMID 24146739, 2013). "Early post infection and prior to development of adaptive immunity, viral titers were significantly increased in liver tissue from fgl2−/− mice compared to the fgl2+/+ mice reaching a maximum 100-fold difference by day 4 pi." (PMID 24146739, 2013). "The expression levels of CD80 and MHC class II on DC from fgl2−/− mice were significantly higher compared to fgl2+/+ mice indicating that targeted deletion of fgl2 leads to increased activation of DC following infection with LCMV WE." (PMID 24146739, 2013).
infection (continued). "We showed that plasma levels of IFNα were significantly higher in fgl2−/− mice compared to fgl2+/+ mice indicating that targeted deletion of fgl2 leads to enhanced innate immune responses to LCMV WE infection." (PMID 24146739, 2013). "The effect of FGL2 on the generation of anti-viral T cell responses was next examined in a secondary infection." (PMID 24146739, 2013). "In this study, we show that infection of fgl2+/+ mice with LCMV WE leads to increased plasma levels of FGL2, which were detected as early as day 2 pi and persisted until day 50 pi." (PMID 24146739, 2013). "The numbers of CD138+CD19lowCD45Rlow plasma cells in the spleen of fgl2−/− mice was comparable to those of the fgl2+/+ mice prior to infection, but following infection, fgl2−/− mice had significantly increased numbers compared to the control mice." (PMID 24146739, 2013). "In this study, we show that infection of mice with Lymphocytic Choriomeningitis Virus WE (LCMV WE) leads to increased plasma levels of FGL2, which were detected as early as 2 days post-infection (pi) and persisted until day 50 pi." (PMID 24146739, 2013). "Levels of the liver inflammatory biomarker ALT were significantly higher in the serum of fgl2−/− mice compared to fgl2+/+ mice at all time points following infection with LCMV WE." (PMID 24146739, 2013). "Therefore, our research results strongly clarify that the lower mortality of CC10-treated mice after MHV-3 infection is due to the lower levels of Fgl2 and decreased fibrinogen deposition." (PMID 30619295, 2018). "Mice which were re-infected with LCMV 45 days post primary infection had higher frequencies of virus specific CD8+ T cells as early as day 2 post re-infection, indicating more robust secondary anti-viral immune responses to re-infection with LCMV WE in fgl2−/− mice compared to fgl2+/+ mice." (PMID 24146739, 2013). "Titers of neutralizing antibodies were undetectable or low in fgl2+/+mice at all the time-points following infection, whereas fgl2−/− mice developed clinically significant titers of neutralizing antibodies towards LCMV WE as early as 12 weeks pi and peaking at week 16 pi." (PMID 24146739, 2013). "However, occasional FGL2-positive cells were detected in the livers of WT mice at 24 h post-MHV-3 infection and these cells were also present, and slightly enhanced in number, at both the 48 h and 72 h time point." (PMID 21750671, 2011). "Following secondary infection, fgl2−/− mice displayed both higher frequency and number of virus-specific CD8+IFNγ+ T cells compared to fgl2+/+ mice at all time points examined." (PMID 24146739, 2013). "The levels of FGL2 expression in sera of E. multilocularis infected (AE-WT) mice were significantly higher, both at 1 and at 4 month(s) post-infection, when compared to non-infected WT-controls." (PMID 25955764, 2015). "Following infection of fgl2+/+ mice with 2×106 PFU LCMV WE, plasma levels of FGL2 increased from basal level of 0.8±0.2 ng/ml reaching a peak of 7.8±0.5 ng/ml on day 8 pi and remained elevated at all time points studied (up to day 50) when compared to uninfected (naive) mice." (PMID 24146739, 2013). "However, IL-18 deficiency does not prevent Bgp1 expression, virus amplification and FGL2 accumulation in the liver following MHV-3 infection, and as the consequence, these mice stay high with fibrinogen deposition, liver damage and hepatocyte necrosis." (PMID 26367131, 2015).
inflammation (2 papers, 2018 to 2020). Aberrant reaction of the microcirculation characterized by movement of fluid and leukocytes from the blood into extravascular tissues. "Moreover, adoptive transfer of WT BMDMs into macrophage-depleted NASH mice led to more severe liver inflammation than that in mice transplanted with fgl2-/- BMDMs." (PMID 32863955, 2020).
FGL2 also shares sentences with these, for which no sentence is quoted: cardiovascular disease (3 papers); colorectal carcinoma (3); pulmonary hypertension (3); autoimmune myocarditis (2); bacteremia (2); injury (2); myocardial infarction (2); nonalcoholic fatty liver (2); abortion (1); acute myeloid leukaemia (1); Alström syndrome (1); amyotrophic lateral sclerosis (1); astrocytoma (1); atopic eczema (1); autoimmune hepatitis (1); bacterial infections (1); bladder cancer (1); brain cancer (1); breast (1); breast tumors (1); cerebral infarct (1); chronic hepatitis B (1); chronic obstructive pulmonary disease (1); clear cell carcinoma (1); Diarrhea (1); eczema (1); endometrial cancer (1); glomerulosclerosis (1); Hirschsprung disease (1); Hyperglycemia (1).
A further 22 diseases each share a sentence with FGL2 in 1 paper.